IGF1R (insulin like growth factor 1 receptor)
Diseases named in the same sentence as IGF1R in open-access papers (continued):
Sharing a sentence is not in itself a finding about the gene and the disease.
brain disease (2 papers, 2015 to 2024). "Some silico analysis implied that some important molecular signaling pathway such as IP3 pathway, IGF1R pathway, cAMP pathway may be associated with cognitive enhancement in animal models of brain disease." (PMID 26722632, 2015).
endocrine disorders (2 papers, 2022 to 2024). "IGF-1R plays an important role in metabolic and endocrine disorders because the tandem IGF-1/IGF-1R is critical in regulating glucose and lipid metabolism." (PMID 39638246, 2024). "Several studies have declared that IGF-1R is necessary for cellular oncogenes and is important in modulating the cell survival, motility, adhesion, and metastasis in multiple tumors and endocrine disorders." (PMID 36233084, 2022). "This review focused on the role of IGF/IGF-1R signaling in preclinical IGF-targeted therapies, including IGF-1R monoclonal antibodies, IGF-1R tyrosine kinase inhibitors, and neutralizing antibodies of IGFs in multiple tumors and endocrine disorders." (PMID 36233084, 2022).
heart diseases (2 papers, 2017 to 2022). "Similarly, Insulin-like growth factor 1 receptor (IGF1R), protects the heart in settings of heart diseases and plays a role in proliferation, cardiac differentiation, and decreases apoptosis in human heart." (PMID 28693530, 2017).
peripheral neuropathy (2 papers, 2020 to 2025). A disorder affecting the peripheral nervous system. "Spinal dorsal horn IGF1 contributes to the preventive effect of EA treatment against cisplatin-induced peripheral neuropathy through neuronal IGF1R signaling in mice." (PMID 41276799, 2025).
psychiatric disorder (2 papers, 2023). A disorder characterized by behavioral and/or psychological abnormalities, often accompanied by physical symptoms. "From our perspective, the study of IGF-2 is interesting in the context of psychiatric disorders because IGF-2 can trigger IGF-1R signaling, as well as IGF-2R signaling, whereby IGF-2 binding may act as a memory enhancer and a pro-cognitive agent through the induction of neurogenesis." (PMID 37894932, 2023). "We identified three male-specific genes (ARSA, IGF1R, and SNX19) and two female-specific genes (LEMD2 and PCP4) in psychiatric disorders." (PMID 37794117, 2023).
respiratory diseases (2 papers, 2005 to 2017). "Oxidant injury, which is implicated in the pathophysiology of a number of respiratory diseases, acutely upregulates IGF-1R expression in the lung." (PMID 15819984, 2005). "Notably, our findings may contribute to understanding the importance of IGF1R as a potential target for future therapeutic approaches in respiratory diseases with persistent damage and inflammation." (PMID 28655914, 2017).
colon polyps (1 paper, 2016). "Predicting the carcinogenic risk of premalignant polyps with fluorescent IGF-1R antibodies can enable individualized treatment for colon polyps, even without tissue sampling and can help avoid unnecessary invasive procedures or repeated treatment." (PMID 26731105, 2016).
gastrointestinal disorders (1 paper, 2024). "The data mining indicated that the primary SOCs for IGF-1R monoclonal antibody were gastrointestinal disorders, and ear and labyrinth disorders, and general disorders and administration site conditions, which was consistent with the primary adverse reactions listed in the instruction." (PMID 39185318, 2024).
gonadal disorder (1 paper, 2017). A non-neoplastic or neoplastic disorder that affects the testis or the ovary. "We speculate that both the increased and decreased IGF1R gene expression may play a role in the etiology of neurological and gonadal disorders." (PMID 28899882, 2017).
head and neck tumors (1 paper, 2016). "Taken together, these results suggest that heterodimerization of EGFR with IGF-1R can lead to increased activity of EGFR and may be an important platform for cetuximab mediated signaling in head and neck tumors that have become resistant to anti-EGFR therapy." (PMID 27716204, 2016).
immune dysfunction (1 paper, 2024). "Our findings reveal that, beyond immune dysfunction, abnormal IGF-1R signaling leading to enhanced adipogenesis is a crucial pathogenic mechanism in TED." (PMID 39704170, 2024).
myopathy (1 paper, 2018). A disease of the muscle in which the muscle fibers do not function properly. "In the present study, using a HEK cell-based model for GNE myopathy, the role of Insulin-like Growth Factor Receptor (IGF-1R) as cell survival receptor protein was studied to counter the apoptotic effect of non-functional GNE." (PMID 29743626, 2018).
osteopathy (1 paper, 2023). "Additionally, osteopathy defects, which are serious complications of T1DM and T2DM, result from interruption of insulin and IGF1R." (PMID 38274107, 2023).
IGF1R also shares sentences with these, for which no sentence is quoted: multiple myeloma (25 papers); fibrosarcoma (6); colorectal adenoma (4); T-cell acute lymphoblastic leukemia (4); B-cell lymphomas (3); carcinoid tumor (3); dilated cardiomyopathy (3); goiter (3); hypertrophic cardiomyopathy (3); memory impairment (3); muscle atrophy (3); Parkinson's (3); preeclampsia (3); skin cancer (3); thyroid nodule (3); type 1 diabetes mellitus (3); allergic asthma (2); atrial fibrillation (2); autism spectrum disorder (2); benign breast disease (2); bile duct cancer (2); chronic myeloid leukemia (2); chronic pancreatitis (2); colon adenocarcinoma (2); embryonal rhabdomyosarcoma (2); endothelial dysfunction (2); ependymoma (2); gastrointestinal tumor (2); hematological neoplasms (2); hyperandrogenism (2).
A further 168 diseases each share a sentence with IGF1R in 2 papers or fewer.